GATA3 (GATA binding protein 3)
Diseases named in the same sentence as GATA3 in open-access papers (continued):
Sharing a sentence is not in itself a finding about the gene and the disease.
colon carcinoma (8 papers, 2015 to 2025). "The MAPK-ERK pathway activation was found to prevent the proteasome-dependent degradation of Fos-related antigen 1 (FRA-1) protein in colon carcinoma cells and GATA3 protein in developing Th2 cells." (PMID 26672753, 2015). "As an alternative to validation with tissue samples, we decided to investigate the biological role of GATA3 in colon cancer within vitro experiments." (PMID 26097693, 2015). "Experimental studies using engineered colon cancer cell lines show that exogenous expression of GATA3 decreases three-dimensional colony growth and invasiveness of colon cancer cells but does not affect two-dimensional proliferation." (PMID 26097693, 2015). "Using a second validated IHC antibody (GATA3 LS), we found strong staining of the epithelial component of both normal colon tissue and colon cancer." (PMID 26097693, 2015). "Experimental studies in colon cancer cell lines indicate that GATA3 expression acts to suppress invasive, aggressive CRC behavior." (PMID 26097693, 2015). "Taken together, these data provide evidence demonstrating that IL-4 and IL-13 upregulate NOX1 in colon cancer cells though the IL-4R/STAT6 pathway, and that GATA3 plays an important role in the transcriptional regulation of NOX1." (PMID 28498822, 2017). "To determine whether GATA3 was expressed in CRC cells or only in T-cells, we stained CRC TMAs as well as matched normal and colon cancer tissue (Datafile 3)." (PMID 26097693, 2015).
diabetes (8 papers, 2010 to 2025). "Genetic variance in GATA3 is linked to the risk of diabetes and GATA3 has a significant impact on regulating the growth of articular cartilage." (PMID 41476995, 2025). "These include transcription factors concerned with the control of: adipogenesis (Pparγ, Klf15, Irf1, Creb1, Egr2, Gata3); lipogenesis (Mlxipl, Srebp1c); inflammation (Jun, Stat3); insulin signalling and diabetes susceptibility (Foxo1, Tcf7l2)." (PMID 21187013, 2010). "The ROC curve for the hub genes indicated that GATA3 and PTEN have a high diagnostic potential for diabetes and OA." (PMID 41476995, 2025). "The immune factors associated with triggering diabetes, including the cytokines of IFN-γ and IL-4, the Thl/Th2 polarization key transcription factors T-bet and GATA-3 were determined and analyzed." (PMID 39847549, 2025). "Our results suggest that targeting GATA-3 could be a promising way to protect the liver and reduce inflammation in obesity-related diseases, potentially leading to new treatments for conditions like fatty liver disease and diabetes." (PMID 41514930, 2025). "Murine models reveal that IL-33 drives the expansion of highly suppressive GATA3+CTLA4+ Tregs that, in turn, prevent the onset of diabetes." (PMID 39704171, 2024).
gastric adenocarcinoma (8 papers, 2014 to 2026). "Another study reported that GATA3 plays an important role in tumor progression of gastric adenocarcinoma, and the downregulation of GATA3 is associated with unfavorable prognosis in primary gastric adenocarcinoma." (PMID 27403158, 2016). "Kaplan-Meier survival curves revealed that reduced expression of GATA3 was associated with poor prognosis in gastric adenocarcinoma patients (P<0.001)." (PMID 24504018, 2014). "Immunohistochemistry analysis indicated that GATA3 expression was significantly decreased in 225 of the 402 (56%) gastric adenocarcinoma cases." (PMID 24504018, 2014). "Using real-time quantitative PCR (RT-qPCR) and immunohistochemical staining methods, GATA3 expression was analyzed in tissue samples from a consecutive series of 402 gastric adenocarcinoma patients who underwent resections between 2003 and 2006." (PMID 24504018, 2014). "In the current study, we estimated the expression of GATA3 in gastric adenocarcinoma by real-time qPCR and immunohistochemistry, in addition to analyzing its clinicopathological and prognostic significance in a relatively large number of human samples." (PMID 24504018, 2014). "This study aims to investigate GATA3 expression and its prognostic significance in primary gastric adenocarcinoma." (PMID 24504018, 2014). "Our data suggest that GATA3 plays an important role in tumor progression and that reduced GATA3 expression independently predicts an unfavorable prognosis in primary gastric adenocarcinoma patients." (PMID 24504018, 2014). "Therefore, in this study, the expression of GATA3 in primary gastric adenocarcinoma was evaluated using real-time quantitative PCR (RT-qPCR) and immunohistochemistry." (PMID 24504018, 2014). "Likewise, in the current study, we observed an exclusively nuclear expression pattern of the GATA3 protein in gastric adenocarcinoma tissues." (PMID 24504018, 2014). "However, to the best of our knowledge, no previous reports exist concerning the expression status of GATA3 and the prognostic value of this protein in primary gastric adenocarcinoma." (PMID 24504018, 2014). "Model B (containing GATA3 expression) confirmed age (P = 0.006), GATA3 expression (P<0.001), depth of tumor infiltration (P<0.001), lymph node metastasis (P<0.001), and distant metastasis (P<0.001) as independent predictors of the overall survival of patients with gastric adenocarcinoma." (PMID 24504018, 2014). "Moreover, we expect that GATA3 may function as a useful target for new therapeutic interventions against gastric adenocarcinoma." (PMID 24504018, 2014). "Histology and immunohistochemical profiling, with estrogen receptor (ER), progesterone receptor (PR), E-cadherin, GATA3, Mammaglobin, and GCDFP-15, favored the diagnosis of lobular breast carcinoma metastasis over primary gastric adenocarcinoma." (PMID 41743390, 2026). "Specifically, using tissue microarray and immunohistochemistry, it was found that GATA3 expression is inversely correlated with metastasis and overall survival in luminal cell carcinoma However, to date, the prognostic significance of GATA3 in gastric adenocarcinoma has not been evaluated." (PMID 24504018, 2014). "We illustrated that GATA3 is expressed at lower levels with respect to both its mRNA and protein in gastric adenocarcinoma tissues compared with corresponding non-cancerous mucosa (P = 0.0014), in agreement with previous statistics shown in other types of tumor samples." (PMID 24504018, 2014). "Additionally, Notch1 had a positive correlation with CD4, GATA3 and STAT5B and a negative correlation with CD59 in gastric adenocarcinoma." (PMID 32028262, 2020).
invasive carcinoma (8 papers, 2009 to 2025). A carcinoma that is not confined to the epithelium, and has spread to the surrounding stroma. "Quantifications reveal that healthy samples contain ≈5% of double positive GATA3+ & panCK+ cells, while DCIS has the highest percentage of GATA3+ & panCK+ cells at ≈50% compared to 45% for invasive carcinomas." (PMID 40470875, 2025). "The expression level of GATA-3 in non-invasive carcinoma (Tis, Ta, and T1) was significantly higher (p = 0.008) than in invasive bladder tumors (T2–T4)." (PMID 27237631, 2016). "FOXA1 was positive (score ≥ 4) in the nuclei of 42% (93 out of 224) of the invasive carcinomas, while GATA-3 was detected in 48% (97 out of 204) of the cases." (PMID 19549328, 2009). "FOXA1 expression was demonstrated in 42% of invasive carcinomas, while GATA-3 was detected in 48% of the cases." (PMID 19549328, 2009). "A vertebral biopsy was performed finding an invasive carcinoma, CK7+/CK20+, TTF1-, PSA-, Thyroglobulin- and GATA3+." (PMID 28494780, 2017). "Patient #2 had a GATA3 mutation in the HER2‐positive in situ and invasive components, which was absent in the HER2‐negative invasive carcinoma component." (PMID 32058674, 2020). "Additionally, most ER-/PR-/AR+ invasive carcinomas with apocrine differentiation exhibited negative expression of TRPS1 and GATA3." (PMID 40822238, 2025).
mesothelioma (8 papers, 2014 to 2025). A usually malignant and aggressive neoplasm of the mesothelium which is often associated with exposure to asbestos. "GATA3 is positive in 58% of mesotheliomas, and its expression in adenocarcinomas of the digestive tract, endometrium, ovary, and prostate is often <10%." (PMID 39605894, 2024). "GATA3 is a useful marker not only for mammary and urothelial but also for renal and germ cell tumors and mesotheliomas." (PMID 34301206, 2021). "However, as other tumors such as chromophobe renal cell carcinoma, basal cell carcinoma, and mesothelioma have been reported to be reactive to GATA3, it is advisable to use more than one marker to confirm the mammary origin of a metastatic carcinoma." (PMID 27672468, 2016). "However, other tumors such as basal cell carcinoma, mesothelioma, and chromophobe carcinoma of the kidney expressed GATA3 as well." (PMID 25400965, 2014). "So, their results suggest that GATA3 is a useful biomarker in the differential diagnosis between PSM and PCL and that sarcomatoid neoplasm that does not stain at all for GATA3 is very unlikely to be a mesothelioma." (PMID 39941848, 2025).
metastatic carcinoma (8 papers, 2016 to 2025). A carcinoma which has spread from the original site of growth to another anatomic site. "The combined application of TRPS1 and GATA3 is the optimal method to confirm that ER-negative or low-expression distant metastatic carcinoma originates from the breast." (PMID 40822238, 2025). "The combined application of TRPS1 and GATA3 is the best method to determine breast origin of ER-negative or low-expression distant metastatic cancers." (PMID 40822238, 2025). "Diffuse and strong nuclear GATA3 immunoreactivity in the tumor cells that replaced the endometrial stroma, indicated a metastatic carcinoma originating from the breast." (PMID 32164210, 2020). "Nevertheless, TRPS1 and GATA3 could be a reliable panel to determine the breast origin of metastatic cancer." (PMID 40822238, 2025). "Thus, if CK20 immunoreactivity is observed in metastatic carcinoma in addition to GATA3, the primary site of the metastatic carcinoma is expected to be the urinary bladder." (PMID 27642214, 2016). "The tumor cells exhibited positive staining for CKAE1/AE3, GATA-3, and GCDFP-15, confirming the diagnosis of metastatic carcinoma of breast origin." (PMID 41332036, 2025). "SOX10, androgen receptor, and GATA3 expression studies have recently been carried out in TNBC, both in primary tumors and in metastatic carcinomas." (PMID 34771579, 2021). "The combination of CAM 5.2 and GATA3 staining suggested the possibility of metastatic cancer, but systemic clinical examinations did not detect any presence of a primary tumor, including urinary bladder, breasts, and salivary glands." (PMID 37007224, 2023). "SOX10, in turn, remains the most stable when comparing the expression between primary and metastatic carcinoma, and in addition, it is capable of allowing the detection of cases in which there is no expression of GATA3." (PMID 34771579, 2021). "Additionally, positive staining for GATA-3 and GCDFP-15 confirmed the breast origin of the metastatic carcinoma, while negative staining for markers such as PAX-8 and CDX2 helped exclude primary ovarian and gastrointestinal origins, respectively." (PMID 41332036, 2025). "Using either NY-BR-1 or GATA-3, rather than mammaglobin and BRST-2 may help confirming breast origin both in primary and in metastatic carcinoma in males." (PMID 29116378, 2018).
mucinous adenocarcinoma (8 papers, 2014 to 2026). An invasive adenocarcinoma composed of malignant glandular cells which contain intracytoplasmic mucin. "This specific immunophenotype - particularly the GATA3 positivity - presents a profound diagnostic trap, as it closely mimics the profile of metastatic mucinous carcinoma of the breast." (PMID 41769426, 2026). "Furthermore, a higher rate of rare types of tumor (Mixed Histology, Mucinous Carcinoma and Medullary Carcinoma) was observed in association with GATA3 mutations." (PMID 33462316, 2021). "Reduced GATA3 expression was also observed in patients with large tumors (P = 0.017), signet ring cell carcinoma or mucinous carcinoma (P = 0.005) and tumors with lymphatic or venous invasion (P = 0.040)." (PMID 24504018, 2014). "Pathological examination of tissue from excisional biopsy of an inguinal lymph node revealed mucinous adenocarcinoma with immunohistochemistry (IHC) positive for cytokeratin (CK) 7, CK20 and GATA3, and negative for CK5/6, CDX2 and p63." (PMID 34997908, 2022).
multiple sclerosis (8 papers, 2014 to 2025). A progressive autoimmune disorder affecting the central nervous system resulting in demyelination. "Its overexpression is also related to T helper cell differentiation in multiple sclerosis, possibly by a mechanism involving SMAD2, GATA3, and FOXO3 genes, whose participation in Th17 cell differentiation, Treg inhibition, and/or other T helper pathways has been underlined." (PMID 29349090, 2017).
Sepsis (8 papers, 2016 to 2023). Sepsis is defined as life-threatening organ dysfunction caused by a dysregulated host response to infection. "The GATA3 rs3824662 AA genotype was significantly associated with sepsis [hazard ratio (HR) = 3.375; P = 0.01]." (PMID 36714653, 2022). "The first cluster corresponded to TFs with decreased activity in pediatric sepsis, and GATA3 and RORA, as well as other TFs previously implicated in the context of inflammatory response." (PMID 34680414, 2021). "Multivariable analysis of GATA3 rs3824662 genotype for association with sepsis risk." (PMID 36714653, 2022). "The development of drug-like molecules or antibodies capable of either preventing the loss of or inducing endothelial GATA3 during critical illness, such as sepsis, could represent causative treatment strategy against capillary leak." (PMID 34337671, 2021). "Therefore, we hypothesized that the risk allele may accelerate the differentiation of Th2 cells and inhibit Th1 cells by increasing the expression of GATA3, ultimately leading to the balance disorder of Th1/Th2, which is more likely to cause sepsis." (PMID 36714653, 2022). "Second, decreased microvascular flow due to sepsis can downregulate GATA3, inhibiting TIE2 transcription." (PMID 38406775, 2023). "In sepsis, changes in the mRNA levels of T-bet, GATA3, and ROR-γT result in the differentiation of Th1, Th2, and Th17 lymphocyte subsets and subsequent changes in secreted inflammatory factors." (PMID 35910903, 2022). "GATA3 is one of the biggest regulons, and most of its genes on both pediatric sepsis networks seem to be related to ncRNAs." (PMID 34680414, 2021). "In our previous studies, the expressions of ANXA1 and GATA-3 were both decreased in the burnt mouse with sepsis." (PMID 27833268, 2016). "It is reported that membrane adhesive protein Annexin-A1 (ANXA1) and transcription factor GATA-3, which were both decreased in sepsis patients, play important roles in the Th1/Th2 shift." (PMID 27833268, 2016). "The GATA3 SNP rs3824662 may have also contributed to the apoptosis of CD4+ T cells in the onset of sepsis, accelerating the progress of sepsis." (PMID 36714653, 2022). "The characteristics of sepsis among GATA3 rs3824662 genotypes in pediatric ALL." (PMID 36714653, 2022). "Thus this study, together with our previous observations of ANXA1, suggests that the ANXA1/FPRL-1 axis and GATA-3 are potential therapeutic targets of the Th1/Th2-mediated immunological suppression in sepsis." (PMID 27833268, 2016). "Our previous animal model observed that ANXA1 and GATA-3 both present the same downtrend in mouse with severe sepsis; this phenomenon may be related with a large number of T cells apoptosis." (PMID 27833268, 2016). "It is proposed that the interactions between ANXA1 and GATA-3 may provide clues to understand the immunosuppression and have potential as new therapeutic targets in immunotherapy after sepsis." (PMID 27833268, 2016). "Exploring the interactions between ANXA1 and GATA-3 may provide clues to understand the immunosuppression and improve the treatment effects of sepsis patients." (PMID 27833268, 2016). "GATA3 rs3824662 was associated with susceptibility in Han Chinese children with pre-B-cell ALL and could be a possible risk factor for poor early treatment response and treatment-related sepsis." (PMID 36714653, 2022). "In the present study, we identified 47 DE-NRGs between sepsis and healthy control in the dataset GSE65682 and screened out 4 hub genes (BACH2, GATA3, LEF1, and BCL2) via various machine learning algorithms." (PMID 37091800, 2023). "In the study, we found that 4 necroptosis-related hub genes (BACH2, GATA3, LEF1, and BCL2) were closely related to sepsis, providing a potential new target for the diagnosis and therapy of sepsis." (PMID 37091800, 2023).
Sepsis (continued). "In conclusion, using machine learning analysis we identified 4 necroptosis-related hub genes (BACH2, GATA3, LEF1, and BCL2), which could be used as the potential di-agnostic and prognostic biological marker in sepsis." (PMID 37091800, 2023). "In the early sepsis stage, TCR trigger GATA-3 upregulation via PI3K-mTOR dependent pathways." (PMID 27833268, 2016).
viral infection (8 papers, 2011 to 2025). "As GATA3 has been implicated in CD8 T cell function, it is possible that a Zeb2/G9a/GATA3 complex is critical for the function of CD8 T cell function during viral infection." (PMID 28443098, 2017). "This validates our results as GATA3 activity should be down-regulated during a viral infection." (PMID 33923155, 2021). "However, after viral infection, previously committed Th2 cells stably co-expressing Gata3 and T-bet show the features of both Th1 and Th2 cells." (PMID 27053161, 2016). "However, viral infection can reprogram also Th2 cells in vivo into a Th2-Th1 cells expressing GATA3 and T-bet simultaneously." (PMID 21624129, 2011). "Thus, an individual, who has overexpression of T-bet, may be more susceptible to viral infections, while an individual, who has overexpression of Gata3, may be resistant to viral infections." (PMID 28874814, 2017).
endometriosis (7 papers, 2014 to 2025). The growth of functional endometrial tissue in anatomic sites outside the uterine body. "Estrogen plays a role in regulating the GATA3 transcription factor and Th2 differentiation in patients with endometriosis." (PMID 40508002, 2025). "Epigenetic alterations of a few genes (DLX5, CDKN1C, PTGER2, and GATA3) are common for endometriosis and obstetric complications." (PMID 34833476, 2021). "Interestingly, eutopic endometrial tissues from patients with endometriosis have higher mRNA levels of GATA-binding protein 3 (GATA3) compared to normal endometrial tissue." (PMID 35935991, 2022). "Therefore, GATA3 integrates estrogen signaling to induce Th2 cytokine expression in endometriotic lesions, thereby promoting endometriosis progression." (PMID 35935991, 2022). "Researchers showed that distal-less homeobox 5—DLX5 (role in tissue damage repair) and GATA binding protein 3 (GATA3) (associated with cell biology), both paternally imprinted genes, were dysregulated in placenta tissues from women with preeclampsia and endometriosis." (PMID 34833476, 2021). "Several studies have also demonstrated a role for GATA3 in the endometrium throughout the menstrual cycle and in women with endometriosis where it may play a role in modulating cytokine expression; however its expression and methylation were not statistically different based on our arrays." (PMID 24603652, 2014).